CCND1 (cyclin D1)
Diseases named in the same sentence as CCND1 in open-access papers (continued):
Sharing a sentence is not in itself a finding about the gene and the disease.
cancer (continued). "In light of the data available, CCND1 is an attractive, multifaceted target for cancer therapy and is worth extensive study to explore its impact as a novel actionable target and when combined with IR." (PMID 34445095, 2021). "The present study demonstrates that USP52 inhibits cancer cell proliferation through down-regulation of cyclin D1 (CCND1) as well as AKT/mTOR signaling pathway inhibition." (PMID 34533198, 2021). "Cyclin D1 is amplified and overexpressed in multiple cancers and the cyclin D1/CDK4/6 holoenzyme complex is stimulated by mitogenic signaling cascades to accelerate cancer cell proliferation." (PMID 34831218, 2021). "The aim of this preliminary study was to define the prevalence and clinical significance of Ki-67 and Cyclin D1 overexpression in primary ER positive invasive breast cancer, while highlighting the existence of intratumor heterogeneity in this type of cancer." (PMID 34394279, 2021). "Cyclin D1, a key regulator in the G1-to-S-phase transition, is overexpressed in a large fraction of human cancers." (PMID 33718159, 2021). "To conclude, we show for the first time that the hAM homogenate decreases proliferation and is also capable of altering the expression of cyclin D1 in cancer urothelial cells." (PMID 34249888, 2021). "cyclin D1, mediating G1 to S phase transition, is a well-established oncogene and important for the development and progression of several cancers." (PMID 33902004, 2021). "There is substantial evidence showing that CCND1 plays an important role in the development of human cancers, including the migration and metastasis of OS." (PMID 34194515, 2021). "Western blot analysis also showed that knockdown of POLE2 inhibited the expression levels of Cancer-related pathway proteins including p-Akt, CCND1, MAPK9, and PIK3CA." (PMID 33644060, 2021). "The over-expression of cyclin D1 in cancer cells is frequently resulting from the deregulation of ubiquitin-dependent proteasomal degradation system." (PMID 35003521, 2021). "Conversely, the knockdown of the activity of a specific deubiquitinase for CCND1 was shown, inducing growth suppression in cancer cells addicted to its expression." (PMID 34445095, 2021). "The TAp63α/miR-141-3p/AUF1/CCND1 axis can support the finding that TAp63α inhibits cancer metastasis and that miR-141-3p serves as an anoikis-resistant factor in cancer (also see Section 2.1.2)." (PMID 33435156, 2021). "The anti-cancer effect of resveratrol is correlated with the damage of mitochondrial function that leads to increased ROS, apoptosis, downregulation of the protein cyclin D1 can fight against OCa." (PMID 34959716, 2021). "Screening for the impact of other amplified cancer genes in HEK293 cells also demonstrated that EGFR, AKT2, CCND1, CCNE1, SKP2, and FGFR3 caused both increased abundance of phosphorylated ZFP36/TTP and ARE-post-transcriptional reporter activity." (PMID 34535639, 2021). "Dysregulation of the CDK4/6-Rb pathway, as with the activation of CCND1/CDK4 or CDKN2A loss, contributes to cancer development and confers resistance of cancer cells to treatment with the MAPK/ERK inhibitors." (PMID 33807122, 2021). "The CCND1 is always overexpressed in cancer and regulates cell cycle transition from G1 phase to S phase along with CCND2 and CCND3." (PMID 34627268, 2021). "Studies have shown that the Wnt/β‐catenin pathway, NF‐κB pathway, Akt/cyclin D1/CDK4 survival signaling pathway, and autophagy are associated with radiological resistance in cancer." (PMID 34766149, 2021). "For example, JMJD3 by promoting cyclin D1 transcription is involved in the development of cancer cells." (PMID 34217316, 2021).
cancer (continued). "The protein level of cyclin D1 was also monitored as a marker for zotatifin activity as well as an additional measure of effects on cancer cell proliferation." (PMID 34900714, 2021). "This suggests the potential of NSC765600 and NSC765691 to inhibit CCND1/CDK4/PLK1/CD44 expressions in cancer." (PMID 34063946, 2021). "In fact, numerous studies have shown that the amplification of CCND1 is a common phenomenon in human cancers." (PMID 34294689, 2021). "It is well known that these genes suppress tumors, known for being inactive in most types of cancer and also for inhibiting genes with oncogenic functions like cyclin D1 or c-Myc." (PMID 34083581, 2021). "Blockade of TCF4/Wnt pathway using a small molecule antagonist suppress the proliferation of the cancer cells in vivo and vitro through targeting c‐Myc, cyclin D1 and surviving." (PMID 33951279, 2021). "Of note, the MAPK signaling pathway can promote cancer cells proliferation via elevating the cyclin D1 (CCND1) expression." (PMID 33681289, 2021). "The known downstream targets of β-catenin, including MMP-9, c-Myc, cyclin D1, etc., are mainly responsible for β-catenin-driven malignancy in cell proliferation, cell cycle progression, and metastasis in cancer biology." (PMID 34545072, 2021). "The most recurrently encountered structural genetic abnormalities in MM affect well-known cancer-associated genes such as MYC and cyclin D1 (CCND1), that supposedly primarily drive malignant proliferation." (PMID 33494394, 2021). "Wnt signaling pathway has been considered one of the main contributors to the hallmarks of cancers due to the constitutive activation of target genes such as cMyc, CCND1, and VEGF." (PMID 33801021, 2021). "Consistent with this, it was shown that down-regulation of cyclin D1 expression restores chemo- and radiation- sensitivity in the cancer cells." (PMID 33444446, 2021). "Lastly, cancer cell proliferation was assessed by immunohistochemical staining of the cell cycle marker cyclin D1." (PMID 34885059, 2021). "β-catenin affects the transcription of c-Myc and Cyclin D1, thereby regulating cellular apoptosis, proliferation, and Lenvatinib resistance of cancer cells." (PMID 33735820, 2021). "Cyclin D1 expression is frequently elevated in cancer, usually through amplification of the CCND1 locus, which is associated with a poor prognosis in solid tumors." (PMID 33494394, 2021). "Functional experiments showed that the anchorage-independent growth ability of cancer cells is enhanced by overexpressing either miR-527 or miR-760, in company with an increase in CCND1 levels." (PMID 33435156, 2021). "The gene expression analysis from the TCGA database showed that CCND1 amplification was significantly related to the upregulation of the mRNA expression of CCND1 across the top nine cancer types." (PMID 34944992, 2021). "Cyclin D1 plays a crucial role in cell cycle regulation, and is constantly overexpressed in cancer through different genomic alterations." (PMID 33708128, 2021). "Taken together, our results suggest that loss of MED13 alters expression of multiple genes belonging to cancer-related pathways, and that products of these genes integrated in functional network centered around cyclin D1." (PMID 33444446, 2021). "WNT2, MSH6, RAF, and Cyclin D1 (CCND1), genes involved in cancer processes, were also differentially expressed after exposure to 10 μM and 30 μM DON." (PMID 34440667, 2021). "The anti-cancer effects of miR-193a-3p are precluded by the repression of multiple target genes, including cancer related genes such as CCND1, KRAS, RASSF1, STMN1, and MCL1." (PMID 33747358, 2021). "Ionising radiation induces a cyclin D1/RAD51 interaction and inhibition of cyclin D1 expression sensitises cancer cells to ionising radiation." (PMID 33520115, 2021). "CCND1 was frequently overexpressed in various kinds of human cancers as a well-known cancer-related gene." (PMID 33996561, 2021).
cancer (continued). "EGFR has been identified as a transcriptional co-activator for several cancer-promoting genes, including cyclin D1, nitric oxide synthase (iNOS), and cyclooxygenase-2 (COX-2)." (PMID 34295309, 2021). "To further evaluate the biological and inhibitory effects of NSC765600 and NSC765691 in cancer, we identified CCND1/CDK4/PLK1/CD44 as potential druggable candidates for both compounds by using online prediction tools." (PMID 34063946, 2021). "It produces a cytostatic effect by modulating p21, p27, Cyclin D1, and Cyclin A proteins in cancer cells." (PMID 34646138, 2021). "The literature proposes a correlation between PIN1 and cyclin D1, in which PIN1 increases cyclin D1 transcription directly or by Jun N terminal Kinase and/or cytokine-nuclear factor (NF)-κB pathways, resulting in increased proliferation of cancer cells." (PMID 33907248, 2021). "Cyclin D1 is upregulated in various cancers including at least one-third CRC and contributes to the development and progression of CRC." (PMID 35003521, 2021). "CCND1 overexpression is known to promote tumorigenesis in various cancers, and CCND1 amplification is a common event in HNSCC resulting in the dysregulation of cell cycle pathways." (PMID 34907286, 2021). "Those receiving an enriched diet showed fewer polyps, low grade dysplastic areas and carcinomas; furthermore, the supplementation also led to a reduction of cleaved caspase-3 and Cyclin-D1 levels." (PMID 34898546, 2021). "STAT3 can regulate the growth cycle of cancer cells by affecting the expression of cyclin D1 and P27." (PMID 32382281, 2020). "Some studies have found that CCND1 can regulate the cell cycle by controlling the G1/S phase transition, and increased expression of CCND1 will lead to the occurrence of cancer." (PMID 32766221, 2020). "A large number of anticancer chemicals have been shown to downregulate cyclin D1 in various cancer cell types by triggering multiple signaling pathways." (PMID 32928152, 2020). "The essential G1-cyclin, CCND1, is a collaborative nuclear oncogene that is frequently overexpressed in cancer." (PMID 32948740, 2020). "Ultimately, we successfully established the PVT1/miR-20b/CCND1 cancer-related ceRNA network, which was not only significantly associated with the prognosis of PC patients but also played key roles in the progression of PC." (PMID 33008376, 2020). "CDK4/6 can trigger G1 entry from quiescence and facilitate G1 progression by combining with cyclin D1 and then promoting cancer cell proliferation." (PMID 32227572, 2020). "Typically, in human cancers, cyclin D1 is aberrantly expressed at much higher levels than cyclin D2 or D3." (PMID 32337233, 2020). "In total, 32 cancer related genes including CCND1, MKI67, HIF1A, CDH1, RRM2, and FOXM1 were subsequently identified through Ingenuity Pathway Analysis." (PMID 32348423, 2020). "A number of studies have been published for expression analysis of RB1 and CCND1 in different cancers including brain cancer." (PMID 32373934, 2020). "Overexpression of cyclin D1 is frequently observed in cancers, including breast, pancreatic and lung cancer." (PMID 33437516, 2020). "Mechanistically, we found ATO induced DNA damage, and nuclear translocation of Cyclin D1 in cancer cells, that are mediated by ROS and Sumoylation of cyclin D1, respectively." (PMID 33046973, 2020). "Previous studies have established p16 inactivation, cyclin D1 overexpression, and functional RB as predictors of palbociclib sensitivity in cancer cells." (PMID 33243298, 2020).
cancer (continued). "For instance, miR-218 can induce cell-cycle arrest at the G1 phase by targeting the 3ʹ-UTR region of CDK6/Cyclin D1, and overexpression of miR-24 increases the percentage of cells in G1 phase in HepG2 and K562 cancer cells." (PMID 32128112, 2020). "In contrast, inhibition of ZNF703 induced cancer cell cycle arrest in the G0/G1 phase (all P < 0.05), which was confirmed by the reduction of cyclin D1 protein." (PMID 33246486, 2020). "Cyclin D1, another common target of phytochemicals, is often overexpressed in various cancer cell types and tumors." (PMID 32928152, 2020). "Recent evidences strongly suggest the role of Cyclin D1 in the resistance to therapy and cancer progression." (PMID 33317149, 2020). "CCND1 is more frequently dysregulated in human cancers and therefore more studied than cyclin D2 or D3." (PMID 32013938, 2020). "Previous cancer genetic study indicated cyclin D1 gene is amplified in 46.4% of the ESCC among the Chinese population." (PMID 33046973, 2020). "In this paper, it was first discovered that miR-193a-3p played an anti-cancer role in HCC by targeting CCND1, and the relationship between miR-193a-3p and CCND1 expression levels in HCC was explored in depth for the first time." (PMID 32095323, 2020). "Cyclin D1 protein, one of the most important oncoproteins in human cancer, accelerates cell proliferation by engaging CDK4/6 to phosphorylate Rb and drive G1–S transition." (PMID 33139730, 2020). "Our results suggested ATO induced cyclin D1 degradation has a similar effect to CDK4/6 inhibitors, caused inhibition of CDK4/6 signaling, induced cancer cell senescence, and inhibited SCC outgrowth in 4NQO induced OSCC and ESCC mouse models in vivo." (PMID 33046973, 2020). "A series of studies demonstrate how Cyclin D1 is essential in the mechanisms involved in the pathogenesis of cancer." (PMID 33317149, 2020). "A CCND1 amplification occurs in many cancer types and correlates with shorter overall survival and inferior outcomes with ICI therapy." (PMID 32903763, 2020). "But there was no consistency on the definition of amplification of genes or the high- or low-expression level of cyclin D1 in various cancer types or within the same cancer type." (PMID 32903763, 2020). "LncRNA CND1/cyclin D1, a cell cycle regulator in many cancers, is transcribed from the cyclin D1 gene promoter region." (PMID 32489713, 2020). "In conclusion, FD extract inhibited the proliferation of the cancer cells by decreasing the expression of CCND1, EGFR, and COX-2." (PMID 32104177, 2020). "Research evidence suggests that the aggressive growth and metastatic behaviors of cancer cells depend on the dysregulation of p16–CDK4/6–cyclin D1–RB signaling." (PMID 33243298, 2020). "Focusing on pantoprazole, we show that it significantly reduced human cancer cell proliferation by inhibiting cellular H+ extrusion, increasing K+ conductance and promoting cyclin D1-dependent cell cycle arrest and preventing STAT3 activation." (PMID 32164284, 2020). "Inversed correlation between p-Stat1 and cyclin D1 was observed in ESCC cancer tissues with IHC staining." (PMID 33046973, 2020). "The expression of CYCLIN D1 (CCND1 gene) decreased in human cancer cells (MCF-7 and HepG2) after 24 h in the presence of 50 μM fruti when compared to vehicle group (MCF-7: 76%; HepG2: 74%)." (PMID 33020521, 2020). "CCNE1 and CCND1 gene amplification was significantly higher in genome doubled cancers, as has been previously observed." (PMID 32823571, 2020). "Ube2S overexpression, by transfecting cDNA into cancer cells, significantly upregulated the expression of β-catenin, cyclin D1, and MMP7 proteins, novel members of the canonical Wnt signaling pathway (p < 0.05)." (PMID 32038111, 2020). "qRT-PCR results showed that, among genes in the cancer-related pathway, Cyclin D1, SDF-1, AXIN, and TCF were all significantly upregulated in FAP tissues compared to normal tissues, indicating their roles in the development of FAP." (PMID 32626748, 2020).
cancer (continued). "Similar to the effect of RPE on cancer cell proliferation, the expression of cyclin D1 and c-myc expression was dose-dependently reduced by RPE in A549 cells and HCT116." (PMID 33158043, 2020). "It is well-described that cyclin-D1 regulates cell cycle transition from G1 to S phase, a process aberrantly dysregulated in human cancers." (PMID 32850305, 2020). "Over-expression of cyclin D1 shortens the G1-S transition, thus promoting tumorigenesis and cancer recurrence in diverse human cancers." (PMID 32131560, 2020). "Cyclin D1, an important regulator of cell cycle, carries out a central role in the pathogenesis of cancer determining uncontrolled cellular proliferation." (PMID 33317149, 2020). "Thirdly, according to our investigation, activations of a variety of oncogenes and deactivations of tumor suppressor genes were observed along with the amplification of CCND1 in different cancer types." (PMID 32903763, 2020). "This review focuses on novel acquisitions regarding Cyclin D1 dysregulation in the cell cycle control, emerging from current research in human cancer." (PMID 33317149, 2020). "Cyclin-D1/D2 are also oncogenic in most cancers including RCC and play role in progression and metastasis." (PMID 32814766, 2020). "Activated STAT3 can promote the transition to G1 phase and the process of cancer transformation by upregulating the expression of cyclin D1." (PMID 32382281, 2020). "Induction of Cyclin D1 degradation is regarded to be a promising avenue for therapeutic intervention of cancer." (PMID 32792963, 2020). "To validate this correlation, we acquired the expression of miR-193a-3p and CCND1 in twenty types of cancer from starBase V3.0." (PMID 32095323, 2020). "In normal cells, Cyclin D1 expression levels are strictly regulated, conversely, in cancer, its activity is intensified in various manners." (PMID 33317149, 2020). "Cyclin D1 and c-myc are well known oncogenes that are overexpressed in cancer cells, driving uncontrolled cell growth and tumor formation." (PMID 33158043, 2020). "Upregulation of both FN1 and CCND1 messenger RNA was related to cancer invasion and mesenchymal phenotype." (PMID 32037399, 2020). "The total amount of cyclin D1 is usually increased in cancer, and it allows the G1/S progression and therefore cell proliferation." (PMID 32164284, 2020). "Recently, emerging evidences have shown that E2F1 and CCND1 are involved in chemoresistance of various cancers." (PMID 32796817, 2020). "By exogenous expression of Cyclin D1 in benign stromal cells, authors found that cell behavior mimics that of cancer stromal cells." (PMID 33317149, 2020). "Among genes in pathways in cancer, Cyclin D1, SDF-1, AXIN, and TCF were all significantly upregulated in FAP tissues compared to normal tissues." (PMID 32626748, 2020). "Genomic profiling of ESCC tumors found 98% patients having amplification in one or more cancer‐relevant genes, as well as the co‐amplification of genes at adjacent chromosome locations, such as CCND1/FGF19 and TERC/SOX2/PIK3CA." (PMID 31851786, 2020). "Following NF-κB inhibition, the cancer-related genes like Bcl-2, Bcl-xL, cyclin D1, IL-6, COX-2 and MMP9 are subsequently downregulated." (PMID 32131560, 2020). "In line with the previous studies using substances with antitumor activity, CCND1 expression was also found to have decreased in the FD extract treated groups following cancer induction using 4NQO." (PMID 32104177, 2020). "MLK3, a MAP3K family member, phosphorylates Pin1 on a Ser138 site to activate its catalytic function and nuclear translocation, driving the cell cycle and promoting cyclin D1 stability and centrosome amplification of cancer cells." (PMID 32296699, 2020). "Cyclin D1 (CCND1) is a well‐known proliferation promoter that accelerates G1/S transition in cancer." (PMID 31951319, 2020).